ADRA2A (adrenoceptor alpha 2A)
Description:
Alpha-2 adrenergic receptors are G protein-coupled receptors for catecholamines that activate the G(i/o) protein pathway, thereby promoting adenylyl cyclase inhibition, ERK1/2 stimulation, and voltage-gated calcium channels suppression. Control a variety of physiological processes, such as regulation of blood pressure, lipolysis and insulin release. ADRA2A and ADRA2C mediates the presynaptic feedback inhibition of neurotransmitter release from noradrenergic nerve terminals in sympathetic and central nervous systems. ADRA2A inhibits transmitter release at high stimulation frequencies, whereas ADRA2C modulates neurotransmission at lower levels of nerve activity (By similarity). The rank order of potency for agonists of ADRA2A is oxymetazoline > clonidine > epinephrine > norepinephrine > phenylephrine > dopamine > p-synephrine > p-tyramine > serotonin = p-octopamine. For antagonists, the rank order is yohimbine > phentolamine = mianserine > chlorpromazine = spiperone = prazosin > propanolol > alprenolol = pindolol.
Synonyms: ADRA2R; ADRAR; ADRA2; ALPHA2AAR; FPLD8
Tractability: Small molecule: an approved drug acts on it; a structure with a bound ligand is known; a high-quality ligand is known; it belongs to a druggable protein family. Antibody: UniProt places it where antibodies can reach, with high confidence; its Gene Ontology location is reachable by antibodies, with high confidence; UniProt predicts a signal peptide or a membrane-spanning region. PROTAC: its protein half-life has been measured; a small molecule that binds it is known. Other modalities: an approved drug acts on it.
Target class: Small molecule receptor (family A GPCR); Adrenergic receptor; Monoamine receptor; Membrane receptor; Family A G protein-coupled receptor
Chemical probes: CHEMBL194173
Safety:
Unwanted effects reported when the protein is acted on. In parentheses: how it was acted on, where the effect was seen, and who reports it.
sedation (Lynch et al. (2017): activation, acute dosing, pancreas, nervous system, cardiovascular, gastrointestinal; Bowes et al. (2012): activation, cardiovascular system, central nervous system; Urban et al. (2012): activation, cardiovascular system, nervous system)
decreased blood pressure (Bowes et al. (2012): activation, cardiovascular system, central nervous system; Lynch et al. (2017): activation, acute dosing, pancreas, nervous system, cardiovascular, gastrointestinal)
decreased heart rate (Lynch et al. (2017): activation, acute dosing, pancreas, nervous system, cardiovascular, gastrointestinal; Bowes et al. (2012): activation, cardiovascular system, central nervous system)
analgesia (activation; cardiovascular system, nervous system; source: Urban et al. (2012))
anesthetic-sparing effect (activation; cardiovascular system, nervous system; source: Urban et al. (2012))
central hypotension (reduction of blood pressure and heart rate) (activation; cardiovascular system, nervous system; source: Urban et al. (2012))
decreased blood insulin (activation, acute dosing; pancreas, nervous system, cardiovascular, gastrointestinal; source: Lynch et al. (2017))
decreased body temperature (activation, acute dosing; pancreas, nervous system, cardiovascular, gastrointestinal; source: Lynch et al. (2017))
decreased gastric emptying (activation, acute dosing; pancreas, nervous system, cardiovascular, gastrointestinal; source: Lynch et al. (2017))
decreased memory (activation, acute dosing; pancreas, nervous system, cardiovascular, gastrointestinal; source: Lynch et al. (2017))
decreased noradrenaline release and sympathetic neurotransmission (activation; cardiovascular system, central nervous system; source: Bowes et al. (2012))
decreased pain (activation, acute dosing; pancreas, nervous system, cardiovascular, gastrointestinal; source: Lynch et al. (2017))
Decreased, Decreased fecundity (inhibition; source: AOP-Wiki)
gastrointestinal prokinetic effects (inhibition; cardiovascular system, nervous system; source: Urban et al. (2012))
hyperglycemia (activation; cardiovascular system, nervous system; source: Urban et al. (2012))
hypothermia (activation; cardiovascular system, nervous system; source: Urban et al. (2012))
increased blood insulin (inhibition, acute dosing; pancreas, nervous system, cardiovascular, gastrointestinal; source: Lynch et al. (2017))
increased convulsions (inhibition, acute dosing; pancreas, nervous system, cardiovascular, gastrointestinal; source: Lynch et al. (2017))
increased gastrointestinal motility (inhibition; cardiovascular system, central nervous system; source: Bowes et al. (2012))
increased gastrointestinal transit (inhibition, acute dosing; pancreas, nervous system, cardiovascular, gastrointestinal; source: Lynch et al. (2017))
increased heart rate (inhibition, acute dosing; pancreas, nervous system, cardiovascular, gastrointestinal; source: Lynch et al. (2017))
increased insulin secretion (inhibition; cardiovascular system, central nervous system; source: Bowes et al. (2012))
increased pupil diameter (activation, acute dosing; pancreas, nervous system, cardiovascular, gastrointestinal; source: Lynch et al. (2017))
memory impairment (activation; cardiovascular system, nervous system; source: Urban et al. (2012))
mydriasis (activation; cardiovascular system, central nervous system; source: Bowes et al. (2012))
weight gain (activation; cardiovascular system, nervous system; source: Urban et al. (2012))
Gene: Protein-coding gene on chromosome 10 (111,077,029 to 111,080,907, forward strand). Ensembl gene ENSG00000150594.
Subcellular location: Cell membrane
Pathways (Reactome):
Signal Transduction: Adrenoceptors; G alpha (i) signalling events; G alpha (z) signalling events
Hemostasis: Adrenaline signalling through Alpha-2 adrenergic receptor
Metabolism: Adrenaline,noradrenaline inhibits insulin secretion
Metabolism of proteins: Surfactant metabolism
Gene Ontology:
Molecular function: alpha-2C adrenergic receptor binding; alpha2-adrenergic receptor activity; epinephrine binding; heterotrimeric G-protein binding; norepinephrine binding; protein binding; protein homodimerization activity; protein kinase binding; thioesterase binding; alpha-1B adrenergic receptor binding; adrenergic receptor activity; G protein-coupled receptor activity
Biological process: adenylate cyclase-activating adrenergic receptor signaling pathway; adenylate cyclase-inhibiting adrenergic receptor signaling pathway; adrenergic receptor signaling pathway; cellular response to hormone stimulus; epidermal growth factor receptor signaling pathway; G protein-coupled receptor signaling pathway; glucose homeostasis; negative regulation of insulin secretion; negative regulation of insulin secretion involved in cellular response to glucose stimulus; negative regulation of lipid catabolic process; phospholipase C-activating adrenergic receptor signaling pathway; positive regulation of cell migration; positive regulation of cytokine production; positive regulation of epidermal growth factor receptor signaling pathway; positive regulation of MAPK cascade; positive regulation of membrane protein ectodomain proteolysis; positive regulation of phosphatidylinositol 3-kinase/protein kinase B signal transduction; positive regulation of wound healing; actin cytoskeleton organization; adenylate cyclase-activating G protein-coupled receptor signaling pathway; adenylate cyclase-inhibiting G protein-coupled receptor signaling pathway; intestinal absorption; negative regulation of calcium ion transport; negative regulation of calcium ion-dependent exocytosis; negative regulation of epinephrine secretion; and 16 more
Cellular component: cytoplasm; plasma membrane; receptor complex; basolateral plasma membrane; axon terminus; dopaminergic synapse; GABA-ergic synapse; glutamatergic synapse; membrane; neuronal cell body; postsynaptic density membrane; postsynaptic membrane; presynaptic active zone membrane
Genetic constraint (gnomAD): Loss-of-function variants: 6 observed, 5.96 expected, observed/expected ratio (o/e) 1.01, 90% interval 0.54 to 1.78. That is too few expected variants to judge how well the gene tolerates losing a copy. Missense variants: 647 observed, 600.57 expected, observed/expected ratio (o/e) 1.08, 90% interval 1.01 to 1.15. Synonymous variants: 345 observed, 276.64 expected, observed/expected ratio (o/e) 1.25, 90% interval 1.14 to 1.36.
Homologues: Orthologues: chimpanzee ADRA2A (99% identical), macaque ADRA2A (97% identical), pig ADRA2A (94% identical), mouse Adra2a (92% identical), rat Adra2a (91% identical), dog ADRA2A (83% identical), tropical clawed frog adra2a (66% identical), zebrafish adra2a (56% identical), guinea pig Adra2a (49% identical), Caenorhabditis elegans ser-5 (21% identical). Paralogues in human: ADRA2C (51% identical), ADRA2B (48% identical), DRD2 (30% identical), ADRA1A (26% identical), ADRA1B (26% identical), ADRB1 (26% identical), ADRA1D (26% identical), ADRB2 (23% identical), ADRB3 (23% identical), GPR101 (15% identical), OR5T2 (14% identical), OR5T1 (14% identical), and 6 more.
Diseases named in the same sentence as ADRA2A in open-access papers:
ADRA2A is named in the same sentence as 90 diseases in open-access papers, as found by Europe PMC text mining. Sharing a sentence is not in itself a finding about the gene and the disease. The quoted sentences say what the papers report.
depression (11 papers, 2013 to 2025). "Specifically, the α-2A adrenergic receptor (Adra2a) and associated adenylyl cyclase (AC)-cAMP activity have been shown to modulate poor executive function and neuroinflammation in depression." (PMID 39532806, 2025). "Consistent with this, loss of ADRA2A is associated with socially withdrawn behaviors, depression and autism; moreover, an increase in ADRA2A has been shown to prevent the withdrawal phenotype and increase novelty-seeking behavior, as observed in ADHD." (PMID 34127022, 2021). "Amitriptyline HCl is an antagonist of the alpha-2A adrenergic receptor (ADRA2A), which belongs to the G protein-coupled receptor family, and is used clinically as a neural system drug to treat depression." (PMID 32176725, 2020). "For instance, ADRB1 and ADRA2A genes linked the four most common cardiometabolic disorders (coronary diseases, hypertension, diabetes, obesity) with BPD and depressive disorder." (PMID 28117839, 2017). "The expression level of the 5-HT1A, DRD1, ADRA-2A, GABA-A α1, CNR1, NR3C2, NOD1, NLRP3 and MC4R; BDNF levels, glial activity and intestinal permeability were determined in chronic stress-induced depression in rats." (PMID 40281288, 2025). "In order to evaluate this possibility, we analyzed ADRA2A and ADRA2C mRNA expression in suicide victims with an antemortem diagnosis of major depression." (PMID 34930904, 2021).
type 2 diabetes (10 papers, 2010 to 2024). "This notion is further supported by the presence of type 2 diabetes susceptibility signals intersecting eQTLs for the ADRA2A, CHRNB4 and P2RY1 genes." (PMID 36897571, 2023). "A genetic variation of ADRA2A (risk A allele for rs553668) is known to cause overexpression of ADRA2A, which aggravates adrenergic suppression of insulin secretion and causes type 2 diabetes." (PMID 25946000, 2015). "In type 2 diabetes, a rare example of a specific gene defect that has been successfully treated with naturally occurring chemical compounds is that of the α2A adrenergic-receptor (α2AAR) encoding gene, ADRA2A." (PMID 28124081, 2017). "Notably, single-nucleotide polymorphisms in and near the ADRA2A gene (encoding α2A-adrenergic receptor) have been correlated with increased fasting glycemia and type 2 diabetes risk; impaired glucose-stimulated insulin secretion is a factor in this increased risk." (PMID 33178692, 2020). "Therefore, ADRA2A inhibitors may be utilized to treat a subset of type 2 diabetes patients who carry the genetic risk variant in ADRA2A gene." (PMID 25946000, 2015). "In fact, one ADRA2A inhibitor drug (Yohimbine) is under phase II clinical trial for treating type 2 diabetes (clinicaltrial.org identifier: NCT01593215)." (PMID 25946000, 2015). "Additionally, the associations of MADD, ADRA2A, IRS1 and FASD1 with type 2 diabetes or its related traits were directional different between two subpopulations." (PMID 21747906, 2011). "The direction of associations for loci ADRA2A, IGF1 and IRS1 were consistent to those observed in the previous GWAS, however none of the remaining loci were associated with type 2 diabetes (P≥0.21), IFG (P≥0.10) or combined IFG/type 2 diabetes (P≥0.22)." (PMID 21747906, 2011). "Although the associations between the SNPs in MADD, ADRA2A, C2CD4B, IGF1, IRS1and FADS1 with fasting glucose or type 2 diabetes were directionally consistent with those observed for white Europeans and of similar magnitude to that observed in the previous GWAS, none reached nominal significance." (PMID 21747906, 2011). "SNPs in or near MADD, ADRA2A, PROX1, FADS1, C2CD4B, IGF1, and IRS1 did not exhibit significant associations with type 2 diabetes or related glycemic traits (P≥0.10)." (PMID 21747906, 2011).
diabetes (9 papers, 2012 to 2025). "For instance, ADRA2A is one of candidate genes for obesity and diabetes and variants in the gene was associated with satiation." (PMID 24533460, 2014). "The query indicated that Bromocriptine functions on ADRA2A (α2A adrenergic receptor), which is related to diabetes through the regulation of pancreatic hormone secretion." (PMID 40001634, 2025). "ADRA2A is closely related to diabetes and is involved in the neuroendocrine regulation of bone resorption." (PMID 38967699, 2024). "Moreover, Adra2a expression was also upregulated specifically in eAT under conditions of obesity and diabetes, pointing towards a key role for this receptor in modulating adrenergic responsiveness of human eAT." (PMID 29138472, 2017).
Obesity (9 papers, 2014 to 2024). Accumulation of substantial excess body fat. "In addition, it is well known that the activation of Adra2a has an antilipolytic effect, and the increased alpha/beta adrenoreceptor ratio as well as the gain of function mutations of Adra2 have been associated with obesity in humans." (PMID 31405230, 2019). "ADRA2A is a regulator of catecholamines, which have been reported as associated with energy metabolism, and gene-regulated catecholamine release may play an important role in obesity." (PMID 31798641, 2019). "Because the pig is a model for human obesity research, ADRA2A is worthy to functionally investigate." (PMID 24533460, 2014). "Notably, variants in the CDKAL1, ADCY3, ADRA2A, and NPY2R genes showed strong associations with metabolic traits such as waist circumference, insulin resistance, and obesity." (PMID 39858569, 2024). "Notably, ADRA2A rs1800544 was linked to HOMA-IR and postprandial insulin levels, consistent with earlier findings that associated this variant with MetS and obesity." (PMID 39858569, 2024). "Polymorphism in ADRA2A is responsible for the development of NIDDM and obesity, but this gene may be identified with insulin resistance." (PMID 30678306, 2019). "Additionally, catecholamine-stimulated whole body lipolysis and lipolysis in subcutaneous adipocytes are blunted in obesity, thereby limiting lipid mobilization and favoring fat accumulation, which suggests that ADRA2A might be involved in fat and energy metabolism." (PMID 31798641, 2019).
Hypertension (8 papers, 2009 to 2025). The presence of chronic increased pressure in the systemic arterial system. "Consistently with our results, a DraI RFLP in the 3′ UTR of ADRA2A and an upstream polymorphism C-1291G have been associated with adiposity and abdominal obesity, as well as with increased hypertension prevalence." (PMID 19562039, 2009). "The second top SNP (rs11195419) highlighted in this study is located within 3′ UTR of Alpha-2A-Adrenergic Receptor (ADRA2A; 10q25.2) and was associated with blood pressure and hypertension in overweight individuals (BMI≥25 kg/m2) and among smokers." (PMID 19562039, 2009). "Clonidine is in a class of medications acting on ADRA2A as an agonist, and it has been approved for the treatment of high blood pressure and attention deficit hyperactivity disorder." (PMID 35992381, 2022). "Clonidine is in a class of medications acting on ADRA2A as an agonist and has been approved for treating high blood pressure and attention deficit hyperactivity disorder." (PMID 35992381, 2022). "miR-30e-5p is found to suppress the expression of hypertension related gene ADRA2A in human endothelial cells." (PMID 30975221, 2019). "In total, 12 markers in 7 genes (ADRA2A, LEP, LEPR, PTGER3, SLC2A1, SLC4A2, SLC8A1) revealed considerable association (P<10−3) either with SBP, DBP, and/or hypertension (HYP)." (PMID 19562039, 2009). "In conclusion, there is substantial evidence that genetic variability in ADRA2A and ADRA2B genes influences α2-adrenoceptor function, leading to hypertension due to modulating vascular resistance, endothelial function, and sodium homeostasis in different cohorts." (PMID 33240096, 2020).